SELENOS (selenoprotein S)
Diseases named in the same sentence as SELENOS in open-access papers:
SELENOS is named in the same sentence as 164 diseases in open-access papers, as found by Europe PMC text mining. Sharing a sentence is not in itself a finding about the gene and the disease. The quoted sentences say what the papers report.
Insulin resistance (27 papers, 2010 to 2025). Increased resistance towards insulin, that is, diminished effectiveness of insulin in reducing blood glucose levels. "Selenoprotein S (SelS) is an important endoplasmic reticulum and plasma membrane-located selenoprotein implicated in inflammatory responses and insulin resistance." (PMID 24225223, 2013). "SELENOS expression in adipose tissue is increased in obese patients and is significantly correlated with anthropometric measures of obesity and insulin resistance." (PMID 37895024, 2023). "Selenoprotein S (SELENOS) has been implicated in the pathology and progression of numerous conditions, including diabetes, dyslipidemia, obesity, and insulin resistance (IR)—all recognized contributors to endothelial dysfunction (ED), a precursor event to diabetes-induced AS." (PMID 38172976, 2024). "Moreover, several genetic polymorphisms in the SELENOS gene were demonstrated to be related to T2DM, serum insulin levels, blood glucose levels, and the homeostasis model assessment of insulin resistance." (PMID 37895024, 2023). "As a target molecule of NF-κB, SELENOS in liver, adipose tissue, and skeletal muscle may participate in the occurrence and development of DM and insulin resistance through the NF-κB signaling pathway." (PMID 28797256, 2017). "The Pearson correlation analysis results confirmed that the expression of SELENOS in omental adipose tissues positively correlated with SAA and HOMA-IR, suggesting that SELENOS expression in visceral adipose tissues participated in the insulin resistance process in T2DM patients." (PMID 28797256, 2017). "SELENOS has different biological functions in different tissues and organs: it exerts antioxidant protection and has anti-ER stress effects in the pancreas and blood vessels, while it promotes the occurrence and development of insulin resistance in the liver, adipose tissue, and skeletal muscle." (PMID 28797256, 2017). "Furthermore, SELENOS knockdown in murine C2C12 myoblasts decreased cell viability and exacerbated ER and oxidative stress responses in the presence of palmitate, suggesting a role for SELENOS in skeletal muscle insulin resistance." (PMID 38172976, 2024).
Obesity (21 papers, 2010 to 2025). Accumulation of substantial excess body fat. "Mounting evidence has shown that selenoprotein S (SelS) plays roles in obesity, IR, glucose and lipid metabolism." (PMID 35347118, 2022). "Indeed, our findings indicated that hepatic-specific deletion of SELENOS accelerated the onset and progression of obesity, impaired glucose tolerance and insulin sensitivity, and increased hepatic TG and diacylglycerol (DAG) accumulation." (PMID 38172976, 2024).
diabetes (20 papers, 2008 to 2025). "SELENOS has been reported to be associated with the risk of diabetes: genetic polymorphisms of SELENOS genes are associated with diabetes risk in the Chinese population." (PMID 35795669, 2022). "In a similar vein, there was no significant disparity in the genotype and allele distribution of SELENOS SNPs (rs4965814, rs28665122, rs34713741, and rs4965373) between type 2 diabetes mellitus patients (n = 170) and healthy controls (n = 100) in a Chinese population." (PMID 38172976, 2024). "Additionally, serum SELENOS could function as a potential biomarker, and SELENOS single nucleotide polymorphisms (SNPs) rs4965814, rs28628459, and rs9806366, might be effective gene markers for atherosclerosis-related diseases in diabetes." (PMID 38172976, 2024). "In vivo, SELENOS expression in liver negatively correlated with blood glucose and serum insulin levels in type 2 diabetes mellitus and metabolic syndrome animal models." (PMID 31880214, 2019). "This interaction posits a mechanistic link between SELENOS and diabetes-induced AS." (PMID 38172976, 2024). "The selenoprotein S (SELS) is a putative receptor for serum amyloid A, and recent studies have suggested that SELS may be a link between type 2 diabetes mellitus and inflammation." (PMID 20619427, 2011).
type 2 diabetes (19 papers, 2011 to 2025). "Interestingly, both vitamin D deficiency and SELENOS dysfunction have been linked to chronic conditions such as type 2 diabetes, cardiovascular diseases, and neurodegenerative disorders." (PMID 40735310, 2025). "Moreover, several tagSNPs in the SELS gene were shown to affect markers of cardiovascular disease risk in European American families enriched for type 2 diabetes and epistasis between interleukin 1 and a SNP in selenoprotein S promoter was shown to modulate susceptibility to rheumatoid arthritis." (PMID 25988760, 2015). "Research on the polygenic animal model of type 2 diabetes, Psammomys obesus, has shown that the expression of SELENOS in the liver is inversely correlated with circulating glucose and insulin levels and directly proportional with plasma TG concentrations." (PMID 38172976, 2024).
viral infections (12 papers, 2016 to 2023). "In humans, selenoprotein S (SelS) has antioxidant ability, but it is unclear whether SelS affects viral infection." (PMID 26943035, 2016).
Alzheimer disease (9 papers, 2017 to 2025). A progressive, neurodegenerative disease characterized by loss of function and death of nerve cells in several areas of the brain leading to loss of cognitive function such as memory and language. "Increased expression of selenoprotein S determines a decrease in tau protein phosphorylation in Alzheimer’s Disease (AD)." (PMID 37958974, 2023).
atherosclerosis (8 papers, 2016 to 2025). A disease characterized by the build-up of fatty material and calcium deposition in the arterial wall resulting in partial or complete occlusion of the arterial lumen. "The SELENOS SNPs rs28665122, rs4965814, rs28628459, rs7178239, and rs12917258 were associated with subclinical atherosclerosis, and SELENOS SNPs rs4965814, rs28628459, and rs9806366 were associated with clinical atherosclerosis." (PMID 28797256, 2017).
ischemic stroke (7 papers, 2008 to 2025). A stroke disorder caused by obstruction of blood flow to the brain, due to thrombotic (local blood clot formation) or embolic (due to a blood clot or other material traveling from another site) event. "Collectively, this two-sample MR study provides evidence that genetically elevated plasma levels of SELENOS are associated with an increased risk of all-cause stroke, ischemic stroke, and ICH." (PMID 40004116, 2025). "In this two-sample MR study utilizing data from large-scale GWASs, our results revealed that genetically elevated plasma SELENOS levels were linked to a higher risk of all-cause stroke, ischemic stroke, and intracerebral hemorrhage (ICH)." (PMID 40004116, 2025). "In a Finnish cohort, variation in the selenoprotein S gene locus was associated with coronary heart disease and ischemic stroke in women." (PMID 30813489, 2019). "They found that carrying SELENOS SNP rs4965814 increased the risk of ischemic stroke by 2.89-fold in Finnish women; in addition, they also confirmed that carrying SELENOS SNP rs9874 increased the risk of ischemic stroke in Finnish women by 3.32-fold." (PMID 28797256, 2017). "Also, two variants in the selenoprotein S gene conferred risk for ischemic stroke in women, p(interaction) = 0.003 and 0.007." (PMID 18974842, 2008). "In summary, this study provides initial genetic evidence linking genetically elevated plasma SELENOS levels to an increased risk of all-cause stroke, ischemic stroke, and ICH, suggesting a potential role for SELENOS in stroke development." (PMID 40004116, 2025).
hepatoma (6 papers, 2011 to 2025). "Furthermore, the silencing of SELENOS via small interference RNA (siRNA) was found to significantly exacerbate the inflammatory response, apoptosis, and oxidative stress in hepatoma HepG2 and Hepa1-6 cells induced by β-mercaptoethanol (an ER stress agent) and lipopolysaccharide (LPS)." (PMID 38172976, 2024). "In hepatoma H4IIE cells, overexpression of SELENOS led to decreased hepatic glucose utilization by reducing glucose uptake, glycogen synthesis and content." (PMID 38172976, 2024).
colon cancer (5 papers, 2009 to 2024). "inhibited SELENOS expression in three colon cancer cell lines and the results showed ER stress markers did not increase even in the presence of the ER stress inducer." (PMID 31880214, 2019).
endothelial dysfunction (5 papers, 2018 to 2024). In vascular diseases, endothelial dysfunction is a systemic pathological state of the endothelium (the inner lining of blood vessels) and can be broadly defined as an imbalance between vasodilating and vasoconstricting substances produced by (or acting on) the endothelium. "Selenoprotein S (SelS) has been identified in endothelial cells and is associated with inflammation; however, its function in inflammation-induced endothelial dysfunction has not been described." (PMID 29805311, 2018).
inflammatory bowel disease (5 papers, 2008 to 2025). A spectrum of small and large bowel inflammatory diseases of unknown etiology. "Several selenoproteins (GPX1, GPX2, GPX3, GPX4, SELENOM, SELENOP, SELENOS, and SELENBP1) are expressed in the intestine, and they may play a role in mitigating excessive immune responses that may lead to inflammatory bowel diseases." (PMID 36969558, 2023).
liver cancer (5 papers, 2013 to 2025). An epithelial or non-epithelial malignant neoplasm that arises from the liver. "In addition, the inhibition of SELENOS expression by glucose in a concentration-dependent manner was also confirmed in in vitro cultured HepG2 liver cancer cells." (PMID 28797256, 2017). "They found that SELENOS overexpression could reduce the activity of the glucose-regulated protein 78 (GRP78) promoter, an ER stress marker protein, in HepG2 liver cancer cells and decrease the GRP78 protein expression induced by TC in HEK293T human embryonic kidney cells." (PMID 28797256, 2017).
Stroke (5 papers, 2009 to 2025). Sudden impairment of blood flow to a part of the brain due to occlusion or rupture of an artery to the brain. "It is well documented that SELENOS plays a pivotal role in regulating inflammation, oxidative stress, and endoplasmic reticulum (ER) stress, all of which typically exhibit reciprocal causation, mutually reinforcing each other, and collectively contribute to the onset and progression of stroke." (PMID 40004116, 2025). "SELENOS, a key player in cellular homeostasis, plays dual roles in stroke pathology, influenced by its impact on oxidative stress, inflammation, and ER stress." (PMID 40004116, 2025). "Selenoprotein S (SELENOS), one of the carrier proteins of dietary selenium (Se), is a key regulator of inflammation, oxidative stress, and endoplasmic reticulum (ER) stress, all of which are implicated in the pathogenesis of stroke." (PMID 40004116, 2025). "However, our findings support a dual role for SELENOS, where at certain levels, it may contribute to stroke risk rather than being solely protective." (PMID 40004116, 2025).
gastric cancer (4 papers, 2009 to 2024). A primary or metastatic malignant neoplasm involving the stomach. "Regarding SELENOS, its polymorphisms were associated with many tumors, such as colorectal and gastric cancer, and were able to affect the expression levels of inflammatory cytokines in plasma." (PMID 32933107, 2020).
Hashimoto thyroiditis (4 papers, 2015 to 2022). An autoimmune disorder caused by the production of autoantibodies against thyroid tissue. "Previous work that was published by our group suggested that there is a link between SELENOS (SEPS1) promoter genetic variation and Hashimoto’s thyroiditis (HT) risk." (PMID 30287753, 2018). "Also, genetic interactions between minor alleles in the selenoprotein S gene (SELENOS) and the nuclear factor erythroid 2-related factor 2 gene (NFE2L2) increase chronic thyroiditis incidences." (PMID 36686463, 2022).
muscular dystrophy (3 papers, 2017 to 2025). Muscular dystrophy (MD) refers to a group of more than 30 genetic diseases characterized by progressive weakness and degeneration of the skeletal muscles that control movement. "Recent studies have identified SELENOS as a novel disease-modifying gene in muscular dystrophy and myopathy by investigating whether genetic depletion of SELENOS in mdx-dystrophic mice exacerbates skeletal muscle inflammation and impairs the structure and function of dystrophic hind limb muscles." (PMID 40507171, 2025).
arteritis (2 papers, 2022 to 2023). An inflammatory process affecting an artery. "Recently, the role of SELENOS in the formation of NETs induced with selenium-deficient arteritis has been shown." (PMID 36362436, 2022).
autoimmune disease (2 papers, 2021 to 2024). A disorder resulting from loss of function or tissue destruction of an organ or multiple organs, arising from humoral or cellular immune responses of the individual to their own tissue constituents. "Notably, certain genotypes associate with autoimmune disease (AID) risk and autoantibody titers, e.g., in selenoprotein S (SELENOS) or selenoprotein P (SELENOP)." (PMID 34445238, 2021).
influenza (2 papers, 2011 to 2021). An acute viral infection of the respiratory tract, occurring in isolated cases, in epidemics, or in pandemics; it is caused by serologically different strains of viruses (influenzaviruses) designated A, B, and C, has a 3-day incubation period, and usually lasts for 3 to 10 days. "Besides, a previous study in humans showed that the mRNA expression levels of selenoprotein S (SEPS1) significantly increased 7 days after an influenza vaccine challenge with Se supplementation." (PMID 34660766, 2021).
insulinoma (2 papers, 2021 to 2024). "Overexpression of SELENOS was shown to protect Min6 β-cells, a mouse insulinoma cell line, from oxidative stress-induced apoptosis, suggesting that SELENOS could be important for insulin secretion and insulin sensitivity." (PMID 38172976, 2024).
steatosis (2 papers, 2022 to 2025). Increased lipid within the cytoplasm of cells. "Conversely, the overexpression of SELENOS in hepatocytes reduced steatosis and improved insulin sensitivity, highlighting the importance of SELENOS in lipid metabolism and insulin signaling." (PMID 39942544, 2025).
aneurysm (1 paper, 2018). Bulging or ballooning in an area of an artery secondary to arterial wall weakening. "The risk of AAA was influenced by specific two-locus effects between the SEPP1, SELENOS, and TXNRD2 genes, which resulted in 50% reduced susceptibility to aneurysm development." (PMID 30188935, 2018).
diabetic retinopathy (1 paper, 2025). "The RHOB gene encoding Ras homolog gene family, member B protein, and SELENOS have recently been identified as biomarkers for diabetic retinopathy." (PMID 41465472, 2025).
glucose metabolism disorder (1 paper, 2022). "Therefore, our results suggested that SELENOS expression might be specifically affected by SELENOF KO and the glucose metabolism disorder observed in young SELENOF KO mice might be partly due to the abnormal elevation of SELENOS expression." (PMID 36358477, 2022).
non-alcoholic steatohepatitis (1 paper, 2022). "The mRNA level of SELENOS in the liver of pigs induced by high fat can be significantly increased, and the expression of SELENOS is negatively correlated with the trend of apoptosis rate and symptoms of non-alcoholic steatohepatitis." (PMID 35624837, 2022).
oophoritis (1 paper, 2025). Inflammation of the ovary, generally caused by an ascending infection of organisms from the endocervix. "Selenoproteins like glutathione peroxidases (GPx‐1, GPx‐3 and GPx‐4), selenoprotein P (SELENOP), and selenoprotein S (SELENOS) play a crucial role in sperm development, maturation, protection of ovarian follicles, and regulating oophoritis and placentitis." (PMID 41268629, 2025).
renal fibrosis (1 paper, 2019). A final common manifestation of a wide variety of chronic kidney diseases characterized by glomerulosclerosis and tubulointerstitial fibrosis. "Thus, we want to use SELENOS as a starting point for revealing the relationship between ER-resident selenoproteins and renal fibrosis." (PMID 31880214, 2019).
cancer (80 papers, 2005 to 2026). A tumor composed of atypical neoplastic, often pleomorphic cells that invade other tissues. "The association between SELENOS gene variation and the risk of cancer and the associations between SELENOS gene variation combined with other gene variations and the risk of cancer still require more studies for investigation and validation." (PMID 28797256, 2017).
tumor (29 papers, 2009 to 2025). "Research indicated that GPX2, GPX4, and TXNRD3 were upregulated and that SELENOP, SELENOS, and GPX3, SELENOK were significantly downregulated in tumor tissues of CRC patients in Ireland compared to controls." (PMID 34769138, 2021).
cardiovascular disease (20 papers, 2011 to 2025). "Se deficiency leads to a decrease in plasma SELENOS levels, which contributes to the development of cardiovascular diseases due to the activation of neutrophils and increased formation of NET." (PMID 36362436, 2022).
infection (20 papers, 2009 to 2025). The state of being infected such as from the introduction of a foreign agent such as serum, vaccine, antigenic substance or organism. "Recently, infection of selenium-deficient Vero E6 cells with SARS-CoV-2 revealed a downregulation of SELENOF, SELENOK, SELENOM, and SELENOS localized in the ER, indicating that infection could adversely affect ER." (PMID 35563199, 2022). "The results presented in the current study provide evidence that genetic variants in regulatory regions (cis-eQTLs) can up-regulate the C3, S100B, and SELENOS gene expression which might activate a prompt resolution of the infection." (PMID 33432064, 2021).
SELENOS also shares sentences with these, for which no sentence is quoted: selenium deficiency (40 papers); metabolic disorders (11); breast carcinoma (9); Hyperglycemia (8); metabolic syndrome (7); prostate carcinoma (7); Sepsis (7); autoimmune thyroid disease (5); colorectal cancer (5); COVID-19 (5); neurodegenerative disease (5); neurological disorders (5); bacterial infection (4); coronary heart disease (4); Hepatic steatosis (4); Infertility (4); ischemia (4); lipid metabolism disorder (4); myopathy (4); Parkinson disease (4); alopecia (3); Cirrhosis (3); diabetic nephropathy (3); fibrosarcoma (3); Hypercholesterolemia (3); Hypertension (3); immune dysfunction (3); Impaired glucose tolerance (3); Nephropathy (3); rheumatoid arthritis (3).
A further 102 diseases each share a sentence with SELENOS in 3 papers or fewer.